STAT3 (signal transducer and activator of transcription 3)
Diseases named in the same sentence as STAT3 in open-access papers (continued):
Sharing a sentence is not in itself a finding about the gene and the disease.
neuroblastoma (continued). "Altogether, these data suggest that miR-323a-3p directly binds and inhibits the expression of STAT3 mRNA and protein levels in neuroblastoma cells." (PMID 37033189, 2023). "AZD9150 also decreased tumorigenicity and increased the chemosensitivity of neuroblastoma cells by inhibiting endogenous STAT3 and STAT3 target genes." (PMID 36918935, 2023). "miR-323a-3p inhibits growth of neuroblastoma cell lines through G1-cell cycle arrest and apoptosis, and the well-known oncogene STAT3 is a direct target of this miRNA." (PMID 37033189, 2023). "Previous scientific studies have suggested that inhibiting the expression of STAT3 can activate the apoptotic machinery, decrease neuroblastoma tumorigenicity, increase chemosensitivity and exert antimetastatic effects on neuroblastoma cells." (PMID 38031104, 2023). "It has been reported that STAT3 plays an important role in tumorigenicity and metastatic effects in neuroblastoma cells." (PMID 38031104, 2023). "AZD9150 was also evaluated in neuroblastoma cells, where it was shown to be able to reduce STAT3 levels; this inhibition of STAT3 determines slow growth and also reduces the number of cellular colonies." (PMID 36012138, 2022). "To assess the effect of homocysteine on leptin signaling, we pre-treated the SH-SY5Y-Ob-Rb human neuroblastoma cell line with homocysteine at 3 and 10 mM and analyzed the phosphorylation of STAT3 induced by leptin (0.01 μg/mL, equal to 0.6 nM)." (PMID 36512575, 2022). "Some CAFs originate from MSCs, and research has shown that CAF-MSCs (CAFs with MSC characteristics) from neuroblastoma (NB) enhance tumour engraftment, growth and resistance to etoposide or melphalan via STAT3 and ERK1/2 signalling in vivo." (PMID 35869057, 2022). "The presence of TAMs upregulated the activation of STAT3 pathway in neuroblastoma tumor cells and administration of JAK/STAT inhibitor AZD1480 reduced TAM-mediated growth of neuroblastoma." (PMID 32983125, 2020). "HNG has neuroprotective effects by activating Erk1/2, Akt, and Stat3 signaling via a gp130 receptor in SH-SY5Y neuroblastoma cells." (PMID 32604799, 2020). "mTOR was shown to phosphorylate STAT3 at Ser727, and then promote its transcriptional activity in neuroblastoma cells." (PMID 31949495, 2020). "In the presence of soluble IL-6 receptor (sIL-6R), IL-6 effectively activated STAT3 in neuroblastoma and prevented drug-induced apoptosis in neuroblastoma in a STAT3-dependent manner." (PMID 32872659, 2020). "In both murine and human neuroblastoma cells, we found that TAMs increased STAT3 activation in neuroblastoma cells and transcriptionally up-regulated the MYC oncogene." (PMID 29207662, 2017). "Examples of studies of CLCF-1 receptor activation and signaling include phosphorylation of gp130, LIFR-β, and STAT3 in human neuroblastoma cells and activation of NFκB and SRE reporter constructs." (PMID 26146641, 2015). "We show here that activated ALK robustly activates STAT3 on Tyr705 in a number of independent neuroblastoma cell lines." (PMID 23889739, 2013). "Maximal suppression of neuroblastoma tumor growth in NOD/SCID mice by NK cells in a microenvironment in which tumor cell STAT3 and SMAD2/3 pathways are active occurs when mice are treated with both lenalidomide and ch14.18." (PMID 23982484, 2013). "In this study, we found that AZD1480-mediated inhibition of the JAK/STAT3 pathway resulted in in vitro and in vivo suppression of tumor growth in neuroblastoma, rhabdomyosarcoma and Ewing sarcoma." (PMID 23531921, 2013). "We investigated ALK, STAT3 and MYCN levels in CLB-GE, CLB-BAR, Kelly and CLB-GA neuroblastoma cell lines upon treatment with STAT3 inhibitors." (PMID 23889739, 2013). "Initially, we employed small interfering RNA (siRNA) targeting STAT3 in a number of neuroblastoma cell lines, including CBL-GE, CBL-BAR, CBL-GA and Kelly cells." (PMID 23889739, 2013).
neuroblastoma (continued). "STAT3 inactivation in neuroblastoma cell lines has been observed in response to various treatments such as Sorafenib and Curcurbitacin." (PMID 21266077, 2011). "In human neuroblastoma cells doxorubicin leads to STAT3 activation that results in apoptosis inhibition." (PMID 16001973, 2005). "In neuroblastoma N2a cells, O-GlcNAcylation inhibits oxidative stress-induced apoptosis by modulating the expression and activity of signal transducer and activator of transcription 3 (STAT3) and forkhead box protein O 1 (FOXO1)." (PMID 41059334, 2025). "Here, we assessed whether astaxanthin could effectively inhibit the proliferation, clone formation, invasion and migration of neuroblastoma cells and increase apoptosis through the STAT3 pathway." (PMID 38031104, 2023). "Together, these data demonstrated that STAT3 is a direct target of miR-323a-3p in neuroblastoma." (PMID 37033189, 2023). "The overexpression of STAT3 is closely related to the tumorigenicity of neuroblastoma." (PMID 38031104, 2023). "Interestingly, inhibition of STAT3 leads to decreased growth and viability of neuroblastoma cell lines, in addition to decreased levels of MYCN in neuroblastoma cell lines carrying ALK mutations." (PMID 34769149, 2021). "STAT3‐S727 phosphorylation by ciliary neurotrophic factor treatment in neuroblastoma cells has been reported to be induced by mTOR kinase, but the mechanism of mTOR pathway regulation by the STAT3 pathway is unknown." (PMID 32495998, 2020). "STAT3 directly mediates the initiation of MYCN transcription in neuroblastoma cells." (PMID 33937011, 2020). "Interestingly, using a model of apoptosis in human neuroblastoma cells, Ulbrich and colleagues observed that argon affected the phosphorylation and binding activity of STAT3, and that inhibition of STAT3 attenuated argon’s anti-apoptotic effect." (PMID 31159847, 2019). "Moreover, BDNF has been shown to promote non-small lung cancer proliferation in an autocrine manner and metastasis of neuroblastoma through STAT3 and PI3K and MAPKsingalling pathway, respectively." (PMID 28604807, 2017). "This work suggests that STAT3 inhibition may be a viable approach in the regulation of MYCN activity in neuroblastoma cells, and may have potential therapeutic value in the future." (PMID 23889739, 2013). "We then investigated whether STAT3 is not only important for initiation of MYCN transcription but also might influence the proliferation of our neuroblastoma cell lines." (PMID 23889739, 2013). "In this context, miR-34a over-expression in neuroblastoma cells and the subsequent inactivation of the STAT3 pathway appears to be one of the potential mechanisms through which miR-34a may exert its apoptotic effect in these cells." (PMID 21266077, 2011). "In neuroblastoma (NB), the activation of the STAT3/AKT axis stimulates CSC properties and EMT, both of which are intrinsically linked to radioresistance." (PMID 40823093, 2025). "Finally, silencing ADGRL4 in a neuroblastoma cell line inhibited ERK/STAT3 signalling." (PMID 41469374, 2025). "Our results suggested that the combined use of NP and DX could be a promising therapeutic strategy for targeting the Jak2/Stat3 pathway in neuroblastoma, offering a potential avenue for enhancing effective treatment and overcoming resistance to conventional therapies." (PMID 39356934, 2024). "This suggests that STAT3 may be an available target for neuroblastoma." (PMID 38031104, 2023). "However, whether neuroblastoma can be inhibited by astaxanthin through the STAT3 pathway has yet to be explored." (PMID 38031104, 2023). "We showed that NP prevents the invasion and proliferation of neuroblastoma SH-SY5Y cells and that this effect is achieved by suppressing Jak2/Stat3 signaling pathway." (PMID 39356934, 2024).
neuroblastoma (continued). "Xenograft and allograft murine models of neuroblastoma showed increased GCSFR expression promoting the proliferation and metastasis of neuroblastoma through GCSF-dependent phosphorylation of STAT3 signaling in CD114+ cells." (PMID 36033452, 2022). "In neuroblastoma cells, STAT3 has been found to directly bind to full-length ALK, which leads to STAT3 phosphorylation." (PMID 34769149, 2021). "Inhibition of STAT3 with antisense oligonucleotide or pharmacological inhibitors reduced MYCN gene expression and decreased neuroblastoma tumorigenicity in preclinical mouse models." (PMID 33937011, 2020). "Leptin (0.5 μg/mL, 15 min) was administered to a SH-SY5Y human neuroblastoma cell line stably transfected with Ob-Rb leptin receptor (SH-SY5Y Ob-Rb), and the cells were analyzed for STAT3 and STAT5 activation." (PMID 27746736, 2016). "Activation of the IL6/STAT3 pathway protects GBM and neuroblastoma cells from drug-induced apoptosis." (PMID 25638155, 2015). "ER stress impaired leptin-induced STAT3 activation and this effect was reversed by flurbiprofen in the SH-SY5Y-Ob-Rb neuroblastoma cell line." (PMID 24421337, 2014). "Given recent observations that ALK regulates MYCN transcription in neuroblastoma cells and collaborates with MYCN in neuroblastoma pathogenesis 34–37, we decided to investigate a role for STAT3 in this process." (PMID 23889739, 2013). "In this analysis, we employed CLB-GE, CLB-BAR, Kelly and CLB-GA neuroblastoma cell lines, measuring their growth in response to treatment with the STAT3 inhibitor FLLL32 or STAT3 siRNA." (PMID 23889739, 2013). "These include STAT3, IGSF4 and CACNA2D3, and they should also be studied in further detail to determine their possible role in neuroblastoma pathogenesis." (PMID 16989664, 2006). "In neuroblastoma and neuroendocrine prostate cancer, activation of the anaplastic lymphoma kinase (ALK) receptor tyrosine kinase up-regulates MYCN transcription through a STAT3-dependent mechanism." (PMID 38748789, 2024). "STRING database analysis predicted that ANXA2 binds to STAT3, and thus, we speculate that STAT3 may be involved in the downstream signalling pathway of Nectin2 and ANXA2 during neuroblastoma pathogenesis." (PMID 36916296, 2023). "Indeed, compared with neuroblastoma, in Ewing sarcoma cDCs showed significantly lower expression of NFKB1 and STAT3, confirming their dysfunctional state and involving previously reported signaling pathways in the observed phenotype." (PMID 37823774, 2023). "When analyzing non-MNA neuroblastoma tumor data, we did not observe a correlation between STAT3 and miR-323a-3p expression (data not shown)." (PMID 37033189, 2023). "In human neuroblastoma cell lines STAT3 mediates the inhibition of apoptosis by IL-6 and the up-regulation of BIRC5 and BCL2L1 by IL-6 two actions probably involved in the drug resistance of some human neuroblastomas." (PMID 28467792, 2017). "Although it was not investigated in this study, it would be of interest to examine the importance of STAT3 phosphorylation in neuroblastoma cells harboring a wild-type nonactive ALK receptor." (PMID 23889739, 2013). "Interestingly, when compared with neuroblasts, the neuroblastomas have more genes in common with the self-renewing neural stem cells (535 versus 145), among others the neurogenesis genes ASCL1, GSS, STAT3, UTP11L, ENAH, APBB2, CDK5RAP2, and LARGE." (PMID 16989664, 2006). "Furthermore, TAMs in non-amplified tumors activate STAT3 in neuroblastoma cells, upregulating c-Myc that reciprocally induces CCL2 secretion, forming a positive feedback loop." (PMID 38087370, 2023). "Furthermore, studies suggest that TAMs can promote tumor progression by upregulating oncogenic MYC expression through activation of the STAT3 pathway in non-MYCN amplified neuroblastoma cells." (PMID 33917501, 2021).
neuroblastoma (continued). "Notably, there is an additional example were bosutinib was similarly repurposed against neuroblastoma, where it was shown capable of suppressing oncogenic activity via targeting multiple signaling pathways including Src/Abl and PI3K/AKT/mTOR, MAPK/ERK, and JAK/STAT3." (PMID 39202022, 2024). "However, the role of miRNA directly targeting STAT3–3′UTR is not yet demonstrated in neuroblastoma." (PMID 37033189, 2023). "Furthermore, it was clear that treatment of neuroblastoma cell lines with either FLLL32 or crizotinib reduced the phosphorylation status of STAT3 to a similar degree, without increasing cleavage of poly(ADP-ribose) polymerase (PARP), which was used as a measure of apoptosis." (PMID 23889739, 2013). "It is also very different from a study in human neuroblastoma cells which suggested that treatment with ciliary neurotrophic factor or a phorbol ester could induce a proteasome-dependent degradation of STAT3 which could be inhibited by MG132 and in which no discrete cleavage products were reported." (PMID 17295906, 2007). "However, inhibition of STAT3 activation significantly retards TAMs mediated tumor growth in subcutaneous neuroblastoma in mice, which suggests that IL-6 is not the key to the growth of neuroblastoma and may be related to the type of tumor." (PMID 33224886, 2020). "While established tumor growth in neuroblastoma xenografts was not inhibited, systemic administration of AZD9150 led to reversal of STAT3-mediated resistance to cisplatin, as indicated by a twofold decrease in the IC50 for cisplatin." (PMID 31671769, 2019). "Ruxolitinib was also effective at blocking the macrophage-dependent STAT3 phosphorylation and MYC up-regulation in MYCN non-amplified human neuroblastoma cells." (PMID 29207662, 2017). "The pretreatment of neuroblastoma cells with LY294002 and PD98059 did not alter the leptin-mediated phosphorylation of STAT3, which indicated that the leptin-induced activation of STAT3 was independent of PI3K and MEK." (PMID 25403445, 2014).
skin cancer (75 papers, 2006 to 2026). "STAT3 activation is strongly implicated in the development of inflammation-associated UVB-induced skin cancer." (PMID 41596287, 2026). "Within the context of cSCC, STAT3 deficiency is sufficient to block tumor formation in the 2-step chemical skin cancer mouse model, wherein tumors develop from within the HF bulge KSC population." (PMID 38916963, 2024). "When12-O-tetradecanolyphorbol-13-acetate was used as thepromoter and 9,10- dimethylbenz-[a-]anthracene was used as an activator,development of skin tumor was entirely opposed in STAT-3-deficient mice." (PMID 32167126, 2020). "IL-17A is also associated with development of skin cancer via STAT3-mediating signaling in tumor and stromal cells, thus stimulating the penetration of myeloid cells into tumor environment." (PMID 30304852, 2018). "Epithelial cell hyperproliferation in TPA-treated skin is impaired in p38γ/δ-deficient mice, accompanied by a reduction in activation of the oncogenic transcription factor STAT3, which is associated with cell proliferation and skin tumour formation." (PMID 26079427, 2015). "STAT3-deficient mice were completely resistant to skin tumor development in a chemical-induced skin tumorigenesis model." (PMID 24380387, 2013). "It is also noteworthy that Stat3 function appears to be necessary for epidermal hyperplasia and susceptibility to skin tumor formation in other transgenic mouse models." (PMID 23577258, 2013). "Among different STAT family members, STAT3 is implicated in tumorigenesis and it plays an important role in skin cancer development." (PMID 22014088, 2011). "However, additional research is needed to evaluate the efficacy and risk profile of STAT3 inhibitors in skin cancer treatment." (PMID 40399946, 2025). "Thus, use of this skin-specific Stat3-deficient mouse model demonstrated that Stat3 was absolutely required for development of skin tumors using the two-stage DMBA-TPA protocol." (PMID 23577258, 2013). "The JAK/STAT3 signaling pathway, crucial in skin cancer progression, presents a potential target for enhancing treatments for advanced skin cancers." (PMID 40399946, 2025). "This modulation of the JAK/STAT3 pathway by CA treatment activated the apoptosis mechanism in a UVB-induced skin cancer model in mice." (PMID 40493253, 2025). "Globally, we observed a remarkable increase of interferon response and JAK/STAT3 signaling in skin tumors." (PMID 40282557, 2025). "Meanwhile, a pronounced infiltration of M2-macrophages and Tregs in skin tumors created an immunosuppressive microenvironment, consistent with the elevated expression of the Stat3 pathway in skin tumors." (PMID 40282557, 2025). "Meanwhile, a pronounced infiltration of Tregs in skin tumors created an immunosuppressive microenvironment, consistent with the elevated expression of the Stat3 pathway in skin tumors." (PMID 40282557, 2025). "Decreased levels of STAT3 phosphorylation and subsequent expression of the oncoprotein c‐Myc, as well as suppressed angiogenesis in skin tumor tissues of mice treated with 17‐oxo‐DHA as compared to controls, were also observed." (PMID 40616290, 2025). "In another study, the role of curcumin‐ and STAT3–siRNA‐loaded liposomes was evaluated in the context of skin cancer therapy." (PMID 38919334, 2024). "RUNX1 maintains the active/phosphorylated form of the oncogene STAT3 by inhibiting SOCS3/4 in skin cancer, thereby increasing cell survival, proliferation, and invasion." (PMID 36551618, 2022). "A similar critical interdependency between STAT3 and Smo‐driven oncogenesis has been reported in SmoM2 murine skin tumors." (PMID 34482626, 2022).